RHOA (ras homolog family member A)
Diseases named in the same sentence as RHOA in open-access papers (continued):
Sharing a sentence is not in itself a finding about the gene and the disease.
colon carcinoma (continued). "In this context, we have previously demonstrated that miR-340-5p can reduce colon cancer cell migration by controlling RhoA activity, indicating that miR-340-5p can be used to regulate colon cancer pathogenesis." (PMID 34295384, 2021). "The RHOA activator (Lysophosphatidic acid LPA) was found to induce colon cancer cell proliferation through β-catenin signaling, while protecting them from apoptosis through ERK, BAD and BCL2." (PMID 33406731, 2021). "Contrary to previous reports, LATS activity is not decreased post cholesterol treatment, demonstrating that cholesterol-RhoA signaling potentially regulates YAP via alternative LATS independent mechanisms in colon cancer cells." (PMID 33637695, 2021). "In colon cancer cells, the inactivation of RHOA accelerated intestinal tumorigenesis through enhancing the Wnt/β-catenin signaling pathway showing the involvement of Rho GTPase in the Wnt signaling pathway." (PMID 34062818, 2021). "In conclusion, these studies suggested RHOA as a potential tumor-promoting factor in colon cancer, with a fundamental role in supporting tumor growth and invasiveness." (PMID 33406731, 2021). "In the present study, we discovered a novel oncogenic lncRNA (i.e., LOC441461) that regulated the growth and motility of colon cancer cells and conferred sensitivity through the RhoA-ROCK signaling activity." (PMID 33126743, 2020). "The NOB supplementation along with atorvastatin suppresses the invasion and migration of colon cancer cells via RhoA downregulation." (PMID 32380783, 2020). "In this context, it is interesting to note that miR-340-5p has been found to target RhoA in squamous and non-small cell lung carcinoma as well as melanocytes although the interaction between miR340 and RhoA in colon cancer cells remains elusive." (PMID 33037251, 2020). "This study demonstrates that miR-340-5p negatively regulates colon cancer cell migration and invasion by targeting RhoA." (PMID 33037251, 2020). "Levels of miR-340-5p and RhoA mRNA varied inversely in serum-free and serum-grown HT-29 and AZ-97 colon cancer cells." (PMID 33037251, 2020). "These novel results suggest that miR-340-5p is an important regulator of colon cancer cell motility via targeting of RhoA and further experiments are warranted to evaluate the role of miR-340-5p in colon cancer metastasis." (PMID 33037251, 2020). "The great antitumor activity of lupeol depends on RhoA inhibition to suppress colon cancer capacity in proliferation and growth." (PMID 32380783, 2020). "It was found transfection with miR-340-5p not only decreased expression of RhoA mRNA and protein levels in HT-29 cells but also reduced colon cancer cell migration and invasion." (PMID 33037251, 2020). "In summary, our study is the first to report the involvement of a novel oncogenic lncRNA, namely LOC441461, in colon cancer growth and cell motility through the modulation of the RhoA/ROCK signaling activity." (PMID 33126743, 2020). "We examined the role of miR-340-5p in regulating RhoA expression as well as cell migration and invasion in colon cancer cells." (PMID 33037251, 2020). "In conclusion, this study demonstrates that miR-340-5p negatively regulates colon cancer cell RhoA activity as well as migration and invasion." (PMID 33037251, 2020). "Targeting this binding site with a specific blocker reversed mimic miR-340-5p-induced inhibition of RhoA activation and colon cancer cell migration and invasion." (PMID 33037251, 2020). "This is consistent with previous reports from our laboratory showing that the knock down of RhoA downregulated cellular adhesion and migration in colon cancer cells." (PMID 31795337, 2019). "In colon carcinoma cells, the translocation of RhoA from the cytosol to the edges of membrane ruffles, as well as the co-localisation with integrin β1, has been reported to regulate cell migration." (PMID 30385434, 2018).
colon carcinoma (continued). "Considered together, these findings suggest that miR-155-5p constitutes a pro-carcinogenic miRNA in serum starved colon cancer cells via promotion of RhoA signaling and migration in response to CCL17 stimulation." (PMID 28146427, 2017). "We found that miR-155-5p is a positive regulator of RhoA mRNA expression and function in serum starved colon cancer cells." (PMID 28146427, 2017). "In summary, our data show that miR-155-5p positively regulates CCL17-induced RhoA activity and migration of serum starved colon cancer cells." (PMID 28146427, 2017). "It is widely held that RhoA acts as a pro-oncogene and is often overexpressed in different kinds of tumors, including colon cancer." (PMID 28146427, 2017). "Accordingly, our results revealed that miR-126 down-regulated the expression of CXCR4 and the critical components involved in RhoA signaling pathway in human colon cancer cells." (PMID 27517626, 2016). "In colon cancer cell lines (HT-29 and SW-620) miR-133b was shown be essential for the inhibitory effects of TAp63 on RhoA, E-cadherin and vimentin, the authors concluded that miR-133b is able to suppress the metastasis of colon cancer." (PMID 27092493, 2016). "We next analyzed the relationships between the levels of CXCR4, components of the RhoA signaling and clinicopathologic characteristics of colon cancer patients." (PMID 27517626, 2016). "Expression of both RhoA G17E and Y42C were able to rescue growth defects of SW948 colon cancer cells grown in 3D culture following knockdown of endogenous RhoA in contrast to re-expression of wild-type RhoA which was unable to rescue." (PMID 27104658, 2016). "Accordingly, our results showed that CXCR4 can reverse the effects of miR-126 on RhoA signaling pathway in colon cancer." (PMID 27517626, 2016). "Silencing of RhoA in colon cancer cell lines promoted proliferation, largely through activation of the Wnt/β-catenin pathway and subsequent upregulation of Myc signaling, and this led to increased metastasis." (PMID 27104658, 2016). "Based on our previous studies, we used tissue microarrays to show that CXCR4 and components of the RhoA signaling pathway were up-regulated in colon cancer tissue compared with those in adjacent normal mucosa tissues." (PMID 27517626, 2016). "For the mechanism of its repression of colon cancer proliferation and invasion, Li reported that miR-126 negatively regulates the expression of CXCR4 and inhibits the RhoA/ROCK (Rho-associated proteinkinase) signalling pathway." (PMID 28536606, 2016). "Taken together, our findings suggested that miR-126 acts as a tumor suppressor by inactivating the RhoA signaling pathway via CXCR4 in colon cancer." (PMID 27517626, 2016). "In this study, we present evidence that reduction in miR-126 expression, up-regulation of CXCR4 and components of the RhoA signaling pathway in colon cancer tissues were significantly correlated with TNM stages, lymph node metastasis and poor clinical outcome." (PMID 27517626, 2016). "Collectively, these results demonstrated that miR-126 acts as a tumor suppressor by inactivating RhoA signaling via CXCR4 in colon cancer." (PMID 27517626, 2016). "Another very recent study using two different mouse models of colon cancer found that mice carrying a dominant negative RhoA transgene (RhoAT19N) had increased tumor burden." (PMID 26030593, 2015). "Integrins are involved in cell adhesion/movement, and Itgb1 has been shown to activate the RhoA-ROCK pathway in colon carcinoma cells." (PMID 25538140, 2014). "The results presented herein suggest decreasing DGKζ expression or function is a potential route to reducing Rac1 and RhoA activity and the migratory ability of colon cancer cells." (PMID 24646293, 2014). "In colon cancer, miR-126 suppresses cancer cell proliferation and invasion via inhibiting RhoA/ROCK signaling pathway." (PMID 24350576, 2013).
colon carcinoma (continued). "Another study indicated that miR-126 suppresses colon cancer cell proliferation and invasion via inhibition of the RhoA/ROCK signaling pathway." (PMID 24312276, 2013). "Evidence presented here indicate that BRAFV600E significantly induces cell migration and invasion properties in vitro in colon cancer cells, at least in part through activation of RhoA GTPase." (PMID 21943101, 2011). "miR340-5p targets RhoA, inhibiting colon cancer cell viability and metastasis." (PMID 39578854, 2024). "Elevated levels of RhoA have been observed in lung, breast, and colon cancers." (PMID 38956424, 2024). "Next, GST pulldown assays were used to measure RhoA activity in colon cancer cells." (PMID 37046308, 2023). "A previous study reported that TNC and HGF could together provide a convergent pro-invasive signal in human colon cancer cells by inactivating RhoA and activating Rac, respectively." (PMID 36765641, 2023). "Additionally, TNC has been shown to have an important role in actin cytoskeleton remodeling by the inhibition of RhoA activation in human colon cancer cells." (PMID 36765641, 2023). "Furthermore, the RhoA-FAK pathway has been shown to be involved in colon cancer cell proliferation and migration." (PMID 35931958, 2022). "Moreover, HMPSNE promoted colon cancer cell apoptosis; endogenously produced CyR61 was found to counteract this effect, at least in part via RhoA activation." (PMID 36113340, 2022). "Studies in colon cancer cell lines demonstrated that the active K-RAS G13D mutant causes a profound disruption of actomyosin structures, such as stress fibers, and decreases NM II activity even in the presence of a high level of active RhoA." (PMID 33670106, 2021). "In the present study, we revealed that intracellular cholesterol could promote YAP expression via the FZD7/PCP/RhoA pathway in colon cancer cells." (PMID 33637695, 2021). "Accordingly, reducing RHOA expression in colon cancer cells could considerably inhibit cell division and invasion, in a xenograft model." (PMID 33406731, 2021). "Based on the considerations above, we hypothesized that miR-340-5p might regulate colon cancer cell migration and invasion via targeting of RhoA." (PMID 33037251, 2020). "Therefore, we suggest that LOC441461 knockdown suppresses cancer cell growth and motility by blocking RhoA/ROCK signaling in colon cancer." (PMID 33126743, 2020). "When RhoA is inactivated, the nuclear translocation of β-catenin is increased and then Wnt/β-catenin signaling could be aroused in human colon cancer cells." (PMID 32244355, 2020). "Knowing that RhoA plays a key role in regulating cancer cell migration, it was of great interest, herein, to investigate the potential role of miR-340-5p in regulating RhoA in colon cancer cells." (PMID 33037251, 2020). "Overexpression of RhoA has been proved in colon cancer[36 ▶]." (PMID 32429645, 2020). "Interestingly, ARHGAP11A expression induced an increase in the relative Rac1 activity by blocking RhoA signaling, which led to an increase in the invasion ability of colon cancer cells." (PMID 33126743, 2020). "Moreover, the inactivation of RhoA resulted in larger and more numerous adenomas and decreased survival in an APC mutation-driven murine colon cancer model." (PMID 32244355, 2020). "As has been previously reported, inactivation of RhoA may promote the translocation of β-catenin into nucleus and increase the size and number of adenomas in colon cancer." (PMID 32244355, 2020). "We suggest miR-223 may promote colon cancer cell invasion and metastasis by downregulating p120, thereby reducing intercellular adhesion, promoting RhoA activity, and activating β-catenin signaling." (PMID 28969027, 2017). "Moreover, knocking down miR-155-5p markedly decreased CCL17-provoked activation of RhoA in colon cancer cells." (PMID 28146427, 2017).
colon carcinoma (continued). "Based on the considerations above, we hypothesized that should be added after hypothesized miR-155-5p might regulate CCL17-induced and CCR4-dependent migration of colon cancer cells via RhoA function." (PMID 28146427, 2017). "Knowing that CCL17-induced colon cancer cell migration is dependent on RhoA signaling, we next asked whether miR-155-5p might regulate CCL17-evoked activation of RhoA." (PMID 28146427, 2017). "Moreover, we observed that AntagomiR-induced knock down of miR-155-5p also attenuated RhoA mRNA expression and activity, suggesting that miR-155-5p is a positive regulator of RhoA in serum starved colon cancer cells." (PMID 28146427, 2017). "In our studies, we demonstrated that restoration of CXCR4 could significantly reverse the effect of miR-126 on the migration, proliferation and invasion of colon cancer cells, and abolish the effects of miR-126 on RhoA signaling." (PMID 27517626, 2016). "We previously found that miR-126 acts as tumor suppressor via RhoA/ROCK inhibition in colon cancer cells, but the precise roles of miR-126 in colon cancer and the underlying mechanisms remain unclear." (PMID 27517626, 2016). "However, reports suggest that reduced RhoA activity is required for EMT in colon carcinoma progression." (PMID 25756282, 2015). "This study demonstrated up-regulated active Rac1, CDC42 and RhoA expression in Hes1-expressing colon cancer cells, whereas down-regulated active Rac1, CDC42 and RhoA expression in Hes1-silencing cells, which indicated that Hes1 induced cytoskeleton reconstruction of colon cancer cells." (PMID 26452029, 2015). "Like Cdc42 and Rac, high protein expression levels of the Rho GTPase RhoA appears to be a frequent event in different types of human tumors, including colon cancer and increased RhoA activity correlates with poor prognosis and recurrence in hepatocellular carcinoma." (PMID 24279335, 2013). "In human colon cancer cells Dia1 can act downstream of RhoA to regulate the actin network." (PMID 21943101, 2011). "Because RhoA has been shown to be involved in migration and dissemination of colon cancer cells, we assessed, using the Matrigel invasion assay, whether FZD7_siRNA affected the in vitro invasion activity of HCT-116." (PMID 19773752, 2009). "Furthermore, we predicted the binding site of ARHGEF12 and found that CUR might inhibit the invasion and migration of colon cancer cells by inhibiting the binding of ARHGEF12 to RhoA." (PMID 37731740, 2023). "However, the distinctive loss of cell definition, contractility and directionality, along with the increase in cell extension and flatness suggested a potential implication of the RhoA Rho GTPase similar to that observed in colon cancer in response to arginine deprivation." (PMID 33423701, 2021). "Thus, knowledge about mechanisms regulating RhoA could be useful to develop strategies to antagonize colon cancer cell migration and invasion." (PMID 33037251, 2020). "Next, we asked whether RhoA could be a target of miR-340-5p in colon cancer cells." (PMID 33037251, 2020). "In addition, this specific TSB also reversed mimic miR340-induced inhibition of colon cancer cell migration and invasion, suggesting that this specific site on RhoA mRNA is functional target of miR-340-5p with a potential significance for the metastatic process of colon cancer." (PMID 33037251, 2020). "Here, we uncover the oncogenic role of LOC441461 in colon cancer cell growth and motility and identify a novel mechanism for LOC441461 knockdown-induced suppression of cancer motility through modulating Ras homolog family member A (RhoA)/Rho-associated protein kinase (ROCK) activity." (PMID 33126743, 2020). "Taken together, these results show that miR-155-5p positively regulates RhoA mRNA levels and translation as well as cell migration in serum starved colon cancer cells and indicate that targeting miR-155-5p might be a useful strategy to antagonize colon cancer metastasis." (PMID 28146427, 2017).
colon carcinoma (continued). "Given that the activity of Rho GTPases is crucial for cancer cell proliferation and motility, and NEK2 enhanced the activity of RhoA and Rac1, we investigated the impact of NEK2 on the proliferation and metastatic behavior of colon cancer cells." (PMID 39768163, 2024). "In colon cancer, GRPR enhances invasion through the RhoA/ROCK pathway, while in prostate cancer, GRPR overexpression promotes a malignant phenotype via activation of AKT1, PKCε, TYK2, and MST1 pathways." (PMID 39768218, 2024). "miR-192 also benefits the prognosis of colon cancer patients by regulating SRPX2, Rab-2A, RhoA-ROCK-LIMK2, farnesoid X receptor, RB1/E2F1 pathway, and NOD2." (PMID 33614788, 2021). "Both RGS2 and RGS4 abolished PAR4-activated ERK phosphorylation, calcium mobilization and RhoA activity, as well as PAR4-mediated colon cancer cell proliferation and related gene expression." (PMID 32517689, 2020). "Next, we found that transfection with miR-340-5p mimic significantly reduced RhoA mRNA and protein levels as well as RhoA-GTP activity in colon cancer cells, suggesting that RhoA is a target of miR-340-5p in colon cancer cells." (PMID 33037251, 2020). "Same miRNA can regulate different RHO GTPases, for example miRNA-185 can affect the protein levels of both RHOA and CDC42 in colon cancer cells, or each RHO GTPase is a specific target; miRNA-155 specifically targets RHOA and miRNA-29 targets CDC42." (PMID 31248017, 2019). "Our findings indicate that the following molecular events rebuild AJCs in adhesion-defective colon carcinoma cells: microtubule disruption activated GEF-H1, and in turn upregulated RhoA." (PMID 29184140, 2017). "Considering the key role of RhoA in cancer cell migration, it was of great interest to examine the role of miR-155 in CCL17-induced colon cancer cell migration in the present study." (PMID 28146427, 2017). "In vivo and in vitro, miR-126 suppressed the invasion and migration of the colon cancer cells by down-regulating CXCR4 and inactivating the RhoA signaling pathway." (PMID 27517626, 2016). "MAPK activation consequently induces RhoA activation and epithelial-mesenchymal-transition, while PI3K activation suppresses RhoA activity in colon cancer." (PMID 24820097, 2014). "In colon cancer cells, rictor gene-silencing induces mesenchymal-epithelial transition (MET) and inhibits cell motility by effects on both RhoA and Rac1." (PMID 24312263, 2013). "RhoC expression is increased during EMT in a colon cancer model and contributes to EMT-induced migration, whereas RhoA levels go down." (PMID 20822528, 2010). "RHOA and its downstream serine/threonine kinase ROCK have been recently known to regulate metastasis in colon cancer cells under the influence of hypoxia, but RHOA–ROCK signaling has not been reported in hypoxic GC cells." (PMID 40600795, 2025). "Regulation of total RhoA protein levels by AAMP has previously only been described in colon cancer cells, not ECs." (PMID 39404373, 2024). "This, for the first time, suggested that CUR might play a role in inhibiting tumor invasion and migration by blocking the binding of ARHGEF12 and RhoA, which provided a theoretical basis for the CUR treatment of colon cancer." (PMID 37731740, 2023). "In colon cancer cells, the transcription factors SMAD family member 4 (SMAD4) and specific protein 1 (SP1) activated RHOA expression, while c-Myc was reported to interfere with the binding of SP1 to the RHOA promoter, leading to downregulation of RHOA expression." (PMID 35563826, 2022). "Their inhibition has been proposed as a strategy to mitigate invasion and migration of colon cancer cells, being involved in the regulation of EMT and cytoskeleton rearrangement, via RhoA and Rac1 signaling, which are members of the GTPases family that regulates actin filament assembly." (PMID 35645325, 2022).